CXCR4 (C-X-C motif chemokine receptor 4)
Diseases named in the same sentence as CXCR4 in open-access papers (continued):
Sharing a sentence is not in itself a finding about the gene and the disease.
endometrial cancer (29 papers, 2010 to 2025). Primary or metastatic malignant neoplasm involving the endometrium (mucous membrane that lines the endometrial cavity). "The authors analyzed the group of 55 endometrial cancer patients and revealed that higher clinical stages of this malignancy are associated with lower levels of CXCR4 expression." (PMID 24416254, 2014). "Our study is in concordance with this finding, showing a higher proportion of cancer stem cell population (CD133+ and CD133+, CXCR4+) in type 2 endometrial cancer with poor prognosis as compared to type 1 endometrial cancer with good prognosis." (PMID 40433700, 2025). "We found that the proportion of cancer stem cell population that expresses CD133 and CXCR4 was higher in type II endometrial cancer than in type I endometrial cancer." (PMID 40433700, 2025). "CD133+CXCR4+ markers were a promising surface marker in isolating cancer stem cell populations from endometrial cancer." (PMID 40433700, 2025). "CXCL12/CXCR4 also has essential roles in the muscular infiltration of endometrial cancer by activating the PI3K/Akt signalling pathway." (PMID 37509322, 2023). "The CXCL12/CXCR4 axis plays a vital role in endometrial cancer’s proliferation, invasion, and metastasis." (PMID 37509322, 2023). "α-smooth muscle actin (α-SMA), another mesenchymal marker, was found to be increased in endometrial cancer cells with CXCR4/CXCL12 treatment." (PMID 36766756, 2023). "We developed a unique procedure to generate a novel orthotopic mouse model of endometrial cancer by ligation of the horn and transmyometrial injection of CXCR4+ Luciferase+ or CXCR4- AN3CA cells." (PMID 35884987, 2022). "C-X-C motif chemokine receptor 4 (CXCR4), for example, has been reported as showing increased expression in several cancers, including endometrial cancer." (PMID 34884984, 2021). "Addition of CXCR4 antagonists to co-cultured studies inhibited these protumoral effects by suppressing the SDF-1α/CXCR4 axis, offering a potential target for therapy in endometrial cancer patients." (PMID 33808627, 2021). "This evidence suggests that the role of SDF-1/CXCR4/CXCR7 axis in the progression of endometrial cancer still remains unexplained." (PMID 24416254, 2014). "The number of published reports on the prognostic value of the components of SDF-1/CXCR4/CXCR7 pathway in endometrial cancer patients is sparse." (PMID 24416254, 2014). "A recently published study of the role of SDF-1/CXCR4 axis in endometrial cancer involved 199 patients, in whom the estrogen receptor status was examined apart from the SDF-1 and CXCR4 expressions." (PMID 24416254, 2014). "The results of sparse published studies dealing with the role of SDF-1/CXCR4/CXCR7 pathway in endometrial cancer are contradictory and inconclusive." (PMID 24416254, 2014). "This study was the first to suggest that SDF-1α/CXCR4 axis plays a role in the invasion of endometrial cancer." (PMID 24416254, 2014). "It follows that the tumour microenvironment may alter CXCR4 expression on T cells in endometrial cancer." (PMID 41243106, 2025). "Nutritional supplements based on Zinc, Prebiotics, Probiotics and Vitamins, amifostine and the oral CXCR4 Inhibitor X4-136 were also reported to be useful in patients treated with pelvic RT not only for cervical and endometrial cancer but also for anal and rectal cancer." (PMID 39198369, 2024). "The fact that most endometrial cancer (EC) patients overexpress the CXCR4 receptor in tumor tissue, especially at incurable advanced stages, opens an avenue for developing novel therapies targeting CXCR4+ EC cells to add new armamentarium against this malignancy." (PMID 36612081, 2022). "In endometrial cancer, CXC motif chemokine receptor 4 (CXCR4) was demonstrated to be highly expressed by some tumour cells." (PMID 38539419, 2024). "The expression of both CXCR4 and CD133 has been reported in all types of human tumours, including endometrial cancer." (PMID 38539419, 2024).
endometrial cancer (continued). "N-cadherin was over expressed when endometrial cancer cells were treated with TGF-β, IL-6, chemokines CCL18, RANK/RANKL/CCL20, and CXCR4/CXCL12." (PMID 36766756, 2023). "The purpose of our study was to investigate the correlation between SDF-1, CXCR4 and CXCR7 protein levels measured by immunohistochemistry with theclinicopathological features and survival of endometrial cancer patients." (PMID 24416254, 2014). "The aim of our study was to investigate the correlation between SDF-1, CXCR4 and CXCR7 protein levels measured by immunohistochemistry with the clinicopathological features and the survival of endometrial cancer patients." (PMID 24416254, 2014). "The aim of this study was to analyze the expression of SDF-1, CXCR4, and CXCR7 proteins in primary endometrial cancer." (PMID 24416254, 2014). "In endometrial cancer, the CXCL12/CXCR4 axis induces proliferation and invasion." (PMID 34322132, 2021). "As far as endometrial cancer, studies on CXCR4 and CXCL12 expression revealed that CXCR4 is overexpressed in endometrial cancers as compared with normal tissues, whereas CXCL12 was overexpressed in normal mucosa." (PMID 20049170, 2010). "Aiming to offer a therapeutic option for the treatment of endometrial cancer (EC) patients currently lacking an effective therapy, we demonstrated that 64.4% of EC patients overexpress high membrane CXCR4 expression, therefore making them candidates for CXCR4-targeted therapies." (PMID 35884987, 2022).
liver cancer (27 papers, 2010 to 2025). An epithelial or non-epithelial malignant neoplasm that arises from the liver. "Recent data showed that CXCR4 expression in tumor vessels is associated with poor prognosis in cancers such as oral and liver cancer." (PMID 36359248, 2022). "This peptide is specific to CXCR4, a receptor that is highly expressed in liver cancer cells, thereby facilitating the targeted delivery of these nanoparticles to liver cancer cells." (PMID 40563405, 2025). "Studies have demonstrated that fucoidan modulates the CXCL12/CXCR4 axis, exerting a dose-dependent inhibitory effect on Huh7 liver cancer cells by reducing CXCL12 expression." (PMID 39206194, 2024). "CXCL12 is a ligand of CXCR4, and the activation of CXCL12/CXCR4 makes M2 polarized macrophages promote liver cancer metastasis by secreting VEGF." (PMID 37511481, 2023). "This study reveals the effects of AnnexinA7 downregulation and upregulation on the SDF1/CXCR4 axis in mouse liver cancer cells in vitro and in vivo." (PMID 29783989, 2018). "The level of cytoplasmic CXCR4 expression closely correlated with tumour size (P=0.003, χ2-test), venous invasion (P=0.006, χ2-test), high Barcelona Clinic Liver Cancer stage (P=0.003, χ2-test) and Tumour, Node, Metastasis (TNM) stage (P<0.001, χ2-test)." (PMID 26404566, 2015). "PLC/PRF/5 cells (AFP-producinger) and HLE cells (non AFP-producinger) were used to further examine the effect of AFP on CXCR4 expression in human liver cancer cell lines in the present study." (PMID 25815363, 2015). "We determined that the expression of CXCR4 in PVTT tissue was greater than that in liver cancer tissue and that the downregulation of CXCR4 by RNA interference significantly impaired the invasive ability of PVTT cells." (PMID 21110890, 2010). "Furthermore, APS inhibited the migration of Treg cells to the tumour microenvironment by blocking the SDF-1/CXCR4 signalling pathway, thereby reversing the immunosuppressive microenvironment in liver cancer and offering a novel strategy for immunotherapy." (PMID 40649307, 2025). "CXCR4 inhibition is able to prevent T cell resistance and may therefore be a target for immunotherapeutic intervention in liver cancer patients." (PMID 37142825, 2024). "Reported preclinical evidence suggests that inflammatory cytokines derived from monocytes or macrophages promoted vascular CXCR4 expression on endothelial cells, while reducing CXCR4 expression by the depletion of macrophages enhanced the anti-tumor impact of sorafenib in liver cancer." (PMID 38787372, 2024). "Overall, these data suggest that CXCR4 antagonism may impair Tregs’ function in liver cancer patients." (PMID 37142825, 2024). "By investigating the impact of COR on the migration and invasive ability of liver cancer cells, it was found that COR reduced the expression of C-X-C chemokine receptor type 4 (CXCR4) and significantly inhibited the migration and invasion of liver cancer cells in a dose-dependent manner." (PMID 39194034, 2024). "Correlation analyses confirmed results from RF learning by showing a significant co-expression of CXCR4 and immune-related genes within the TCGA database and several independent validation cohorts, especially in prostate (PRAD) and liver cancer (LIHC)." (PMID 36672341, 2023). "Several studies have demonstrated that CXCR4 and SDF-1 play a critical role not only in guiding metastasis, but also in the development of liver cancer." (PMID 31752959, 2019). "In our study, we focused on the effect of the CXCL12/CXCR4 axis on HCC CTCs, from a new perspective, to illustrate the significance of CXCR4 antibody in precision targeted therapy of liver cancer." (PMID 31752959, 2019). "Herein, CXCR4 blocking by peptide R29 impairs the suppressive function of Tregs in both HCC and CRLM patients, suggesting that CXCR4 antagonism is a possible strategy for liver cancer patients." (PMID 37142825, 2024).
liver cancer (continued). "As CXCR4 is overexpressed in HCC/CRLM tumor/TME cells, CXCR4 inhibitors may be considered for double hit therapy in liver cancer patients." (PMID 37142825, 2024). "However, in contrast to other cancer types, so far only three studies have identified and experimentally proved target genes of miR-622 in liver cancer (i.e., mitogen-activated protein 4 kinase 4 (MAP4K4), CXC chemokine receptor 4 (CXCR4), and kirsten rat sarcoma (KRAS)." (PMID 33803354, 2021). "The expression changes of VEGFC/D-VEGFR3/NRP2 and SDF1/CXCR4 are almost completely identical between tumor cells and normal cells, between high and low lymph node metastatic potential of liver cancer cells as well as between downregulation and upregulation of AnnexinA7 (unpublished data)." (PMID 29783989, 2018).
lung adenocarcinoma (26 papers, 2011 to 2025). A carcinoma that arises from the lung and is characterized by the presence of malignant glandular epithelial cells. "Another study showed that a CXCR4 antagonist significantly suppressed acquired resistance to gefitinib in a lung adenocarcinoma cell line harboring EGFR mutations." (PMID 35729596, 2022). "Gefitinib promotes migration and epithelial‐to‐mesenchymal transition of lung adenocarcinoma cells harboring EGFR mutation by enhancing CXCR4 expression." (PMID 34555268, 2021). "Regarding lung adenocarcinoma histologic subtypes, it has been reported that the cytomembranous expression of CXCR4 in lung adenocarcinoma is associated with metastasis and patient survival." (PMID 30103827, 2018). "We also indicated that EGF stimulated a significant increase in the expression of CXCR4 in lung adenocarcinoma cells harboring the EGFR-L858R mutation." (PMID 26338423, 2015). "Furthermore, high expression of CXCR4 was significantly associated with poorer survival in lung adenocarcinoma patients (P < 0.001)." (PMID 30103827, 2018). "Finally, we demonstrated that clinical samples of lung adenocarcinomas harboring the EGFR-L858R mutation exhibited increased surface expression of CXCR4." (PMID 26338423, 2015). "Thus CXCL12, which binds to its cognate receptor CXCR4 expressed by Treg, has been implicated in the recruitment of Treg in a number of tumours including ovarian cancer, adenocarcinoma of the lung, malignant mesothelioma, and the myelodysplastic syndromes." (PMID 21521526, 2011). "Sex differences in ERβ, CXCL12, and CXCR4 expression have also been demonstrated in lung adenocarcinomas, with tumors from premenopausal women having greater expression than tumors from postmenopausal women and men." (PMID 41463203, 2025). "A remarkable increase in the survival rate of patients with lung adenocarcinoma was observed due to a notable increase in CXCR4 expression." (PMID 38911372, 2024). "We identified 30 CXCR4-related immunomodulators in lung adenocarcinoma (LUAD) and lung squamous cell carcinoma (LUSC) and constructed immune prognostic signatures based on CXCR4-related immunomodulators and CXCR4-related mutant genes." (PMID 36308553, 2023). "CXCR4 showed sex-dependent overexpression in lung adenocarcinomas and the signal was shown to be higher in premenopausal women compared to postmenopausal women and men." (PMID 36550527, 2022). "Taken together, all these results indicate that CXCR4 silencing regulates the hallmarks of the metastasis process by inhibiting colony formation, cell proliferation, migration and invasive in lung adenocarcinoma cell line." (PMID 32368286, 2020). "Results showed that the median expression value of CXCR4 was 0.576 (interquartile range, 0.371-0.757) in 41 lung adenocarcinoma tissues." (PMID 32368286, 2020). "Exo_circRNA_0056616 was detected in both PC-9/CXCR4-shRNA cells and lung adenocarcinoma plasma at significantly higher levels than in the corresponding control (P < 0.001)." (PMID 32368286, 2020). "Further studies are needed to elucidate the detailed mechanisms by which AIB1 regulates CXCR4 expression in lung adenocarcinoma." (PMID 30103827, 2018). "To confirm the association between CXCR4 and the EGFR-L858R mutation, we performed an EGFR mutation analysis of cancer cells in MPEs from 12 lung adenocarcinomas and analyzed the surface expression of CXCR4 by flow cytometry." (PMID 26338423, 2015). "Additionally, pairwise analysis revealed that high expression of CXCR4, β-catenin, and PPARδ correlated positively with 75 human lung adenocarcinoma tissues, which was predictive of poor prognosis." (PMID 33637678, 2021). "Furthermore, western blot was performed for CXCR7 and CXCR4 protein expression in human lung adenocarcinoma cell line A549 and large cell lung cancer cell line H460.Human umbilical vein endothelial cells (HUVEC) were used as a normal control." (PMID 33129326, 2020).
lung adenocarcinoma (continued). "Furthermore, higher expression levels of exo-hsa_circRNA_0056616 in plasma correlated with higher protein levels of CXCR4 in lung adenocarcinoma tissue." (PMID 32368286, 2020). "In addition, hsa_circRNA_0056616 was found to be present at higher levels in PC9 lung adenocarcinoma cells and their exosomes following the silencing of CXCR4 with shRNA." (PMID 32368286, 2020). "To determine whether CXCR4 is functionally involved in AIB1-induced lung adenocarcinoma cell aggressiveness, we silenced CXCR4 by using siRNA in A549-AIB1 cells." (PMID 30103827, 2018). "Furthermore, we found a significant positive association between the expression of AIB1 and CXCR4 in lung adenocarcinoma patients (183 cases), and the co-overexpression of AIB1 and CXCR4 predicted the poorest prognosis." (PMID 30103827, 2018). "Importantly, we demonstrated that AIB1 enhances the migratory and metastasis abilities of lung adenocarcinoma cells by up-regulating the expression of chemokine receptor type 4 (CXCR4), an important downstream target." (PMID 30103827, 2018). "Furthermore, a positive correlation between the overexpression of AIB1 and CXCR4 was observed in our cohort of lung adenocarcinoma tissues." (PMID 30103827, 2018). "Rescue experiments and in vitro assays were performed to investigate whether the invasiveness of AIB1-induced lung adenocarcinoma was mediated by C-X-C motif chemokine receptor 4 (CXCR4)." (PMID 30103827, 2018). "CXCR4 was identified as a potential downstream target of AIB1 in lung adenocarcinoma." (PMID 30103827, 2018). "To investigate whether AIB1 could affect the metastatic potential of lung adenocarcinoma cells in vivo and whether this effect could be mediated by CXCR4, we performed in vivo metastasis assays using a Balb/c nude mouse model." (PMID 30103827, 2018). "The authors also observed that CXCL12 correlated with a higher degree of tumor inflammation and suggested that the concomitant presence of activated TILs CD4+CXCR4+ CD69+ might influence tumor progression by shaping the immune cell population infiltrating lung adenocarcinomas." (PMID 35740564, 2022). "However, it is unknown whether CXCR4 is a functional downstream target in aggressive AIB1-mediated lung adenocarcinoma." (PMID 30103827, 2018). "Studies have shown that CCR6/CCL20 drives proliferation and migration in lung adenocarcinoma via autocrine/paracrine mechanisms, while the CXCL12/CXCR4 axis promotes OSCC invasion and distant metastasis—with CXCR4 blockade reducing lymph node metastasis." (PMID 41445742, 2025). "C-X-C motif chemokine receptor 4 (CXCR4) plays an important role in the cell proliferation and metastasis of lung adenocarcinoma." (PMID 33946224, 2021). "A stable PC9/CXCR4-shRNA and PC14/CXCR4-shRNA knockdown lung adenocarcinoma cell lines were established and subjected to functional assays (cell proliferation, colony formation, migration and invasion) for phenotype changes." (PMID 32368286, 2020). "High expression levels of HIF-1α, CXCR4 and SDF-1α were also detected in both lung adenocarcinoma and squamous cell carcinoma." (PMID 25843954, 2015). "Preferential accumulation of CXCR4 positive Treg, and its correlation with tumour CXCL12 expression, has also been previously demonstrated in adenocarcinomas of the lung and malignant mesothelioma." (PMID 21521526, 2011). "Cell studies of lung adenocarcinoma have revealed that estrogen can induce overexpression of CXCR4, which could support tumor growth and metastasis through the CXCL12/CXCR4 pathway." (PMID 41463203, 2025). "CAFs isolated from lung adenocarcinoma tumors promoted EMT via production of stromal-derived factor-1 (SDF-1), making it possible to identify C-X-C chemokine receptor type 4 (CXCR4)/β-catenin/peroxisome proliferator-activated receptor gamma (PPARδ) signaling in this process." (PMID 35873564, 2022).
lung adenocarcinoma (continued). "In addition, lung adenocarcinoma patients with high expression of both AIB1 and CXCR4 displayed the poorest survival, whereas patients with low expression of AIB1 and CXCR4 had the best survival (P < 0.001)." (PMID 30103827, 2018). "C-X-C motif chemokine receptor 4 (CXCR4), which plays an important role in the cell proliferation and metastasis of lung adenocarcinoma, has also been demonstrated to be a transcriptional target of AIB1 involved in promoting cell proliferation in breast and bladder cancers." (PMID 30103827, 2018).